CMTM6 (CKLF like MARVEL transmembrane domain containing 6)
Diseases named in the same sentence as CMTM6 in open-access papers (continued):
Sharing a sentence is not in itself a finding about the gene and the disease.
pancreatic adenocarcinoma (5 papers, 2022 to 2024). "Comprehensive analysis, together with the pancreatic adenocarcinoma (PAAD) dataset from The Cancer Genome Atlas (TCGA), revealed that the ANTXR1, CMTM6, ITGB6, PIGR, and PTGS2 genes were significantly upregulated in GEM‐resistant PDAC cell lines." (PMID 39488785, 2024). "However, it is still unknown what function CMTM6 serves in pancreatic adenocarcinoma (PAAD)." (PMID 37726578, 2023).
colon adenocarcinoma (4 papers, 2020 to 2024). "CMTM6 expression was higher in 275 colon adenocarcinoma (COAD) tissues than in 349 control tissues, and CMTM6 expression was also higher in 92 rectum adenocarcinoma (READ) tissues than in 318 control tissues (P < 0.05)." (PMID 39218981, 2024).
lymph node metastasis (4 papers, 2021 to 2025). "In LUAD, the expression of CMTM6 was obviously upregulated and was significantly associated with T stage (p = 0.008) and lymph node metastasis (p = 0.018)." (PMID 36643629, 2023). "Based on the clinical samples we collected, we analyzed the correlation between CMTM6 expression and patient age, sex, tumor differentiation, T stage and lymph node metastasis in the LUAD group." (PMID 36643629, 2023). "High expression of CMTM6 and PD-L1 was significantly correlated with Borrmann type, lymph node metastasis, peritoneal metastasis, and TNM staging (all P values were < 0.05)." (PMID 33509216, 2021). "Notably, CMTM6 expression lacked associations with age, sex, tumor differentiation, or lymph node metastasis." (PMID 38495487, 2024). "The results showed that CMTM6 expression was significantly correlated with tumor T stage (chi-square: 9.729, df: 2, p = 0.008) and lymph node metastasis (chi-square: 5.593, df: 1, p = 0.018) and had no clinical correlation with other clinical indicators." (PMID 36643629, 2023).
pancreatic cancer (4 papers, 2021 to 2023). "The potential clinical significance of the ATP11B-CMTM6 complex in pancreatic cancer evaluated by TCGA data sets revealed that ATP11B was significantly correlated with tumor stage and pathologic grade, while CMTM6 was associated with the pathologic grade." (PMID 35288467, 2022). "The significant correlation among ATP11B, CMTM6, and PD-L1 was confirmed in clinical samples of pancreatic cancer." (PMID 35288467, 2022). "In a previous study, Burr and colleagues coimmunoprecipitated CMTM6 from digitonin lysate of pancreatic cancer cells and subjected it to mass spectrometry to explore the potential interacting partners of CMTM6." (PMID 33434185, 2021). "Taken together, these results suggested that CMTM6 might be involved in the ATP11B action on PD-L1 in pancreatic cancer." (PMID 35288467, 2022). "Moreover, CMTM6 was negatively associated with activated CD8 +T cells, while positively correlated with PD-L1 expression in pancreatic cancer and many others." (PMID 35288467, 2022). "More importantly, in pancreatic cancer, oncolytic peptide LTX-315 promotes anti-pancreatic cancer immunity by targeting the ATP11B-PD-L1 axis which is dependent of CMTM6-mediated lysosomal degradation." (PMID 37726578, 2023).
stomach adenocarcinoma (4 papers, 2020 to 2024). "In the scRNA-Seq data from primary gastric adenocarcinoma, CMTM6 showed high expression on epithelial cells, T cells, B cells, and macrophages, while CMTM4 was specifically localized on epithelial cells." (PMID 34680324, 2021).
cervical cancer (3 papers, 2024 to 2025). A primary or metastatic malignant neoplasm involving the cervix. "In this work, we report that increased levels of soluble CMTM6 and PD-L1 were found in the plasma of patients with cervical cancer compared to a group of healthy donors." (PMID 39335098, 2024). "We report for the first time that CMTM6 is found in exosomes in cervical cancer patients, and that the exosome fraction of plasma exhibits higher levels of CMTM6 and PD-L1 concentrations compared to the exosome-free fraction." (PMID 39335098, 2024). "We identified CMTM6 and PD-L1 in the total lysate of cells derived from cervical cancer, i.e., SiHa, HeLa, and CaSki." (PMID 39335098, 2024). "In the current study, we report, for the first time, the presence of soluble CMTM6 in cervical cancer." (PMID 39335098, 2024). "We again performed an ELISA, but now using plasma fractions from healthy donors (n = 10) and fractions from patients with cervical cancer (n = 20) to determine the levels of CMTM6 per fraction." (PMID 39335098, 2024). "Both results are consistent with the idea that CMTM6 and PD-L1 are present together in different cervical cancer cell lines, as has been seen in other cancers and cell line models of cancers." (PMID 39335098, 2024). "Once we observed that CMTM6 and PD-L1 were increased in the plasma of patients with cervical cancer, we decided to fraction the plasma into exosome-free and exosome-enriched fractions." (PMID 39335098, 2024). "In the analysis between the different cell lines, the highest expression of total and membrane PD-L1 was correlated with the highest expression of total and membrane CMTM6, both in CaSki cells, a model of metastatic cervical cancer." (PMID 39335098, 2024). "In cervical cancer patients and cervical cancer-derived cell lines, we found that the expression of CMTM6 and PD-L1 are positively correlated; both patients and cell lines with higher levels of CMTM6 showed higher levels of PD-L1." (PMID 39335098, 2024). "As CMTM6 was found in the total lysates of the cell lines derived from cervical cancer, flow cytometry (both intracellular and traditional membrane) was used to quantify the relative expression of CMTM6 in these two locations." (PMID 39335098, 2024). "Soluble CMTM6 was found to be elevated in plasma from patients with cervical cancer, with a nearly three-fold increase in patients (966.27 pg/mL in patients vs. 363.54 pg/mL in controls)." (PMID 39335098, 2024). "Our objective was to determine whether CMTM6 is found in plasma derived from cervical cancer patients and its subcellular localization in cell lines." (PMID 39335098, 2024). "CMTM6, a member of the CKLF like MARVEL transmembrane (CMTM) gene family, has emerged as a critical orchestrator of oncogenic processes, yet its specific role in cervical cancer (CC) remains insufficiently characterized." (PMID 40761779, 2025). "It is unknown if CMTM6 is present in the plasma of patients with cervical cancer, and if it has non-canonical subcellular localizations in cell lines derived from cervical cancer." (PMID 39335098, 2024).
liver cancer (3 papers, 2022 to 2025). An epithelial or non-epithelial malignant neoplasm that arises from the liver. "CMTM6 expression was downregulated in liver cancer samples compared with that in normal liver tissue samples." (PMID 35304440, 2022).
ovarian carcinoma (3 papers, 2022). A malignant neoplasm originating from the surface ovarian epithelium. "The infiltration of dendritic cells was closely associated with CMTM6 expression in ovarian cancer." (PMID 35958549, 2022). "IHC verified that CMTM6 is highly expressed in ovarian cancer tissues and is closely related to PD-L1." (PMID 36110202, 2022). "With the use of the CCLE database, we discovered that CMTM6 was overexpressed in all cell lines of ovarian cancer." (PMID 35174213, 2022).
breast tumors (2 papers, 2022 to 2025). "Like CMTM6, CMTM7 was shown to be a new lead candidate for regulating PD-L1 in breast tumors undergoing EMT." (PMID 40179060, 2025). "Here, we provide our perspective on the involvement of CMTM6 and CMTM7 as new lead candidates for the regulation of PD‐L1 in breast tumors undergoing an epithelial to mesenchymal transition." (PMID 35575054, 2022).
clear cell renal cell carcinoma (2 papers, 2022 to 2025). "And in clear cell renal cell carcinoma (ccRCC), CMTM6 silencing leads to increased CD4 + and CD8 + T cell infiltration in mouse models, which in turn promotes anti-tumor immunity." (PMID 36698778, 2022).
squamous cell carcinoma (2 papers, 2021 to 2024). A carcinoma arising from squamous epithelial cells. "Furthermore, the level of CMTM6 expression exhibited associations with tumor histological types, specifically, squamous cell carcinoma displayed higher expression level compared to adenocarcinoma (p=0.021)." (PMID 38495487, 2024). "Therefore, targeting CMTM6 can be a useful strategy to overcome therapy resistance in advanced squamous cell carcinomas." (PMID 33434185, 2021).
adrenocortical carcinoma (1 paper, 2020). "High CMTM6 expression was an unfavorable factor for patient OS in adrenocortical carcinoma (ACC) (p = 0.0023), LGG (p < 0.001), mesothelioma (MESO) (p = 0.048), and PAAD (p = 0.0036)." (PMID 33552963, 2020).
atherosclerosis (1 paper, 2022). A disease characterized by the build-up of fatty material and calcium deposition in the arterial wall resulting in partial or complete occlusion of the arterial lumen. "Several risk markers related to the immune response that have key roles in atherosclerosis were identified, including the top aging marker MMP8, disease markers KIR3DL1 and MAGEA6, network markers based on degree (RBM10, PJA2, and CMTM6), and network markers based on betweenness (IRAK1 and VAMP8)." (PMID 35706446, 2022).
diffuse large B-cell lymphoma (1 paper, 2020). "Our results indicated that MSI-H occurred the most frequently in UCEC, lymphoid neoplasm diffuse large B-cell lymphoma (DLBC), and COAD, and CMTM6 expression was positively associated with MSI-H in COAD, ESCA, SARC, and STAD." (PMID 33552963, 2020).
Hodgkins lymphoma (1 paper, 2025). A heterogeneous group of malignant lymphoid neoplasms of B-cell origin characterized histologically by the presence of Hodgkin and Reed-Sternberg (HRS) cells in the vast majority of cases. "Our findings exhibited significant correlations in Hodgkin's lymphoma between CD247, CMTM6, CD25, ENTPD1, MBL2, and CD40." (PMID 40360443, 2025).
malignant glioma (1 paper, 2024). A grade III or grade IV glioma arising from the central nervous system. "High CMTM6 expression in NSCLC correlated with lower overall survival rates, consistent with findings in malignant glioma patients." (PMID 38495487, 2024).
ovarian endometrioid adenocarcinoma (1 paper, 2022). An endometrioid adenocarcinoma arising from the ovary. "We noticed that high CMTM6 expression in ovarian serous adenocarcinoma was linked to preferable OS and progression-free survival (PFS), but in ovarian endometrioid adenocarcinoma, high-expressed CMTM6 only exhibited decent OS." (PMID 35174213, 2022).
periodontitis (1 paper, 2024). An acute or chronic inflammatory process that affects the tissues that surround and support the teeth. "MR analysis corroborated the inferences drawn from scRNA-seq, identifying ten causal gene markers associated with periodontitis, including LIMA1, PEA15, TMEM158, CMTM6, PDP1, FFAR4, VAC14, and ENHO." (PMID 39830509, 2024).
uterine cancer (1 paper, 2020). Primary or metastatic malignant neoplasm involving the uterine corpus and/or the cervix. "Among them, CMTM6 mutation frequency was the highest in uterine cancer." (PMID 33552963, 2020).
tumor (75 papers, 2018 to 2026). "Studies have demonstrated that the loss of CMTM6 results in a dramatic reduction in PD-L1 expression, significantly impairing the tumor’s ability to evade immune responses." (PMID 40507229, 2025). "In recent years, CMTM6 has additionally been associated with M2 macrophage polarization, tumor proliferation, metastasis, and reduced survival time." (PMID 39335098, 2024). "In this model, a pool of CMTM6-proficient and -deficient AML cells were subjected to CAR-T treatment, and we observed a preferential survival of CMTM6-deficient tumor cells." (PMID 37683639, 2023). "The group with high CMTM6 expression showed a positive association with various types of tumor-infiltrating cells." (PMID 36643629, 2023). "To include CMTM6 expression on tumor and associated immune cells, we scored CMTM6 analogously to PD-L1 by calculating its CPS, which itself has its weaknesses." (PMID 38067301, 2023). "The deletion of the CMTM6 gene will cause the degradation of PD-L1 protein and reduce its expression of the surface of tumor cells." (PMID 35845949, 2022). "Univariate analysis showed that CMTM6 expression was strongly associated with the tumor size (P = 0.027), TNM stage (P = 0.037), BCLC stage (P = 0.026) and postoperative recurrence (P = 0.022)." (PMID 35304440, 2022). "We further examined the association of CMTM6/4 expression with the tumor burden and found that high levels of CMTM6 in the epithelial and mesenchymal regions were positively associated with the tumor burden and cell proliferation (Ki-67)." (PMID 34680324, 2021). "Given the crucial role of CMTM6 in tumor-related immune responses, we investigated the association between pan-cancer CMTM6 expression patterns and tumor immune microenvironments." (PMID 33552963, 2020). "CMTM4 and its homolog CMTM6 encode transmembrane proteins that positively regulate the PD-L1 protein pool in human tumor cells and dendritic cells." (PMID 32117236, 2020). "High CMTM6 expression is also associated with poor prognosis in malignant gliomas, which is caused by the inhibition of T-cell-mediated anti-tumor immunity." (PMID 31754330, 2019). "The impact of CMTM6 on macrophage polarization and its association with tumor progression were systematically evaluated through a series of in vitro and in vivo experiments, focusing on the induction of M2a macrophage polarization and activation of the mTOR signaling pathway." (PMID 40761779, 2025). "Moreover, the association between CMTM6 and tumor-infiltrating immune cells (TIICs) was identified at the mRNA level." (PMID 36643629, 2023). "Importantly, in both scenarios, manipulating CD58 levels through knockout and overexpression eliminated the difference in T cell activation between cocultures with either CMTM6-proficient or CMTM6-deficient tumor cells." (PMID 37683639, 2023). "Then, we systematically investigated the association involving CMTM6 and the immunological traits within the tumor microenvironment (TME) of PAAD, including immune pathways, immunomodulators, immune infiltrating cells, inflammatory activities, and immunotherapy response prediction." (PMID 37726578, 2023). "Also, CMTM6 was the first CMTM family member associated with tumor immune escape, which regulated endocytic recycling and degradation of PD-L1." (PMID 36110202, 2022). "Subsequently, we analyzed whether CMTM6 was associated with tumor development in two cell subsets of GBM." (PMID 36698778, 2022). "All of these indicate that CMTM6 expression is associated with tumor development and may be a new target for tumor research." (PMID 36698778, 2022). "However, coexpression of CMTM6 in tumor cells and PD-L1 in stromal cells was associated with longer OS in patients with colorectal cancer." (PMID 34065396, 2021). "CMTM6 was highly expressed in HCC, which suggested that CMTM6 overexpression might be associated with HCC tumour progression." (PMID 33757532, 2021).
tumor (continued). "Studies suggest that CMTM6 may modulate the activity of tumor-associated macrophages (TAMs), natural killer (NK) cells, and dendritic cells, thereby shaping the immune landscape of the tumor microenvironment." (PMID 40191195, 2025). "The transmembrane protein CMTM6 promotes plasma membrane expression of the immune checkpoint protein PD-L1, a key suppressor of anti-tumor immunity." (PMID 41634378, 2026). "Targeting CMTM6 has been proposed as a strategy to enhance tumor cell killing by reducing PD-L1 surface expression." (PMID 41634378, 2026). "The intricate regulatory roles of DRG2, TRAPPC4, HIP1R, and CMTM6 in PD-L1 trafficking and stability present compelling opportunities for therapeutic intervention to enhance anti-tumor immunity." (PMID 40507229, 2025). "circ-0000512 sponges miR-622, leading to upregulation of CMTM6, which inhibits PD-L1 ubiquitination, reducing T cell killing activity and promoting tumor progression." (PMID 40739089, 2025). "Taken together, WWP2 knockdown suppresses HCC tumor growth and promotes senescence in vivo, and these effects are abrogated by CMTM6 knockdown, confirming our cellular findings." (PMID 41387673, 2025). "Macrophage depletion alone produced a tumor-inhibitory effect comparable to that observed with CMTM6 knockdown." (PMID 40761779, 2025). "This highlights CMTM6 as a key regulator of the tumor microenvironment, particularly in modulating immune cell dynamics." (PMID 40761779, 2025). "Afterwards, the WB analysis indicated CMTM6 low-expression in tumor tissues and IHC showed that CMTM6 knockdown inhibited the Ki67 expression." (PMID 40761779, 2025). "First, the elevated expression of CMTM6 in tumor cells promotes the proliferation, migration, and invasion of CC." (PMID 40761779, 2025). "CMTM6 also influences the interaction between tumor cells and immune cells within the tumor microenvironment." (PMID 40191195, 2025). "We constructed a coculture system to elucidate the function of tumor exosomal CMTM6 internalized by TAMs (TAMs/WT−Exos or TAMs/Exos-CMTM6 KO)." (PMID 40761779, 2025). "Within our research of CC, a fascinating observation ensued, revealing that CMTM6 proficiently instigates the autonomous progression of tumor cells through an autocrine mechanism." (PMID 40761779, 2025). "This functional interplay was corroborated in vivo, as WWP2 depletion enhanced tumor cell senescence and suppressed tumor growth, an effect that was partially rescued by concurrent CMTM6 knockdown." (PMID 41387673, 2025). "Mounting evidence implicates that CMTM6 in sculpting an immunosuppressive tumor microenvironment (TME)." (PMID 40761779, 2025). "Based on the in vitro data above, we further investigated the role of WWP2 and CMTM6 via xenograft tumor models in vivo." (PMID 41387673, 2025). "Tumor size was measured by a caliper on different days, and the data revealed that CMTM6 shRNA suppressed HCT116 tumor growth in mice (P < 0.0001)." (PMID 39218981, 2024). "Those harboring CMTM6‐knockout cells developed the smallest tumor, whereas those harboring CMTM6‐overexpressing cells developed the largest tumors." (PMID 39488785, 2024). "Recently, CMTM6 has been found to stabilize PD-L1 on the plasma membrane of some tumor cells, favoring tumor immune system evasion." (PMID 39335098, 2024). "Our results revealed that shRNA-mediated CMTM6 knockdown effectively inhibited CRC tumor growth in immunocompromised mice and CRC liver metastasis in immunocompetent mice." (PMID 39218981, 2024). "IHC staining of the tumor slices indicated that high expression of CMTM6 increased the proliferation of GEM‐resistant PDAC cells in vivo and inhibited their apoptosis." (PMID 39488785, 2024). "CMTM6 acts as a key regulator of PD-L1 in various tumor cells, binding to PD-L1 and maintaining its expression on the cell surface." (PMID 38223763, 2024). "The CMTM6 protein also appears to increase the half-life of the PD-L1 protein and to modulate anti-tumor immunity." (PMID 37726578, 2023).